LUZP4 (leucine zipper protein 4)
Description:
Export adapter involved in mRNA nuclear export in cancer cells. Binds and enhances the RNA-binding activity of the nuclear RNA export factor NXF1. Can restore mRNA export function in cells compromised by loss of mRNA export adapters.
Synonyms: CT-28; CT28; HOM-TES-85; CT-8
Tractability: No criterion of Open Targets' tractability assessment is met for any kind of drug.
Gene: Protein-coding gene on chromosome X (115,289,715 to 115,307,563, forward strand). Ensembl gene ENSG00000102021.
Subcellular location: Nucleus; Cytoplasm
Pathways (Reactome):
Metabolism of RNA: Transport of Mature mRNA derived from an Intron-Containing Transcript; mRNA 3'-end processing
Gene Ontology:
Molecular function: protein binding
Biological process: mRNA export from nucleus
Cellular component: cytoplasm; nucleus; transcription export complex
Homologues: Orthologues: chimpanzee LUZP4 (97% identical), chimpanzee LUZP4 (95% identical).
Diseases named in the same sentence as LUZP4 in open-access papers:
LUZP4 is named in the same sentence as 16 diseases in open-access papers, as found by Europe PMC text mining. Sharing a sentence is not in itself a finding about the gene and the disease. The quoted sentences say what the papers report.
melanoma (3 papers, 2015 to 2021). A malignant, usually aggressive tumor composed of atypical, neoplastic melanocytes. "The striking exception was malignant melanoma where Luzp4 expression was very high for many patients." (PMID 25662211, 2015). "This is consistent with the earlier qualitative observation of Luzp4 expression in multiple melanoma samples." (PMID 25662211, 2015). "Whilst Luzp4 is up-regulated in a range of tumours, it appears preferentially expressed in melanoma cells where it is required for growth." (PMID 25662211, 2015). "Here, we show that the CTA Luzp4 is an mRNA export factor required for efficient growth of melanoma cells." (PMID 25662211, 2015). "To identify cells suitable for further studies on Luzp4, we screened various cancer cell lines for expression of Luzp4 and found that the melanoma cell line MeWo had readily detectable expression." (PMID 25662211, 2015). "LUZP4 is an mRNA export adaptor that is highly silent in normal tissues other than testes, and is frequently activated in cancers, such as lung cancers, ovarian cancer, melanoma, and multiple myeloma 64,65." (PMID 33854615, 2021). "Here, we have extended that analysis of the Luzp4 expression profile in cancer cells and found it is expressed in a wide variety of cancer types, but particularly high levels of expression are observed in melanoma cells." (PMID 25662211, 2015). "LUZP4, also called CT-8 or HOM-TES-85, is an mRNA export adaptor required for melanoma proliferation." (PMID 33224957, 2020). "Therefore, at least two types of cancer cells share the requirement for Luzp4 for efficient growth and, given its restricted expression profile in non-disease states, it may be an appropriate target for development of drugs or immunotherapies to treat MM or melanoma." (PMID 25662211, 2015).
multiple myeloma (2 papers, 2015 to 2021). "Recent work identified Luzp4 as commonly up-regulated in multiple myeloma (MM) cell lines and the bone marrow of MM patients, a cell-type absent from our screen of tumours." (PMID 25662211, 2015).
breast carcinoma (1 paper, 2016). "LUZP4 was identified as a high degree gene in all breast cancer networks, except in the HER2-enriched." (PMID 27920729, 2016). "Similarly, we identify LUZP4, a gene barely explored in breast cancer, playing a role in transcriptional networks with subtype-specific relevance." (PMID 27920729, 2016). "In order to illustrate how the same genes may have different roles in different breast cancer manifestations, we selected, based on their degree in each breast cancer network, the CNR2, LCK, and LUZP4 genes." (PMID 27920729, 2016). "Furthermore, unlike the two previously discussed genes, LUZP4 has not been extensively studied in the context of breast cancer." (PMID 27920729, 2016).
neurological paraneoplastic syndromes (1 paper, 2024). "More recently, leucine zipper protein 4 (LUZP4) antibodies have been described in patients with neurological paraneoplastic syndromes, presenting as rhombencephalitis, limbic encephalitis, seizures and/or motor neuronopathy." (PMID 39555481, 2024).
seminoma (1 paper, 2015). A radiosensitive malignant germ cell tumor found in the testis (especially undescended), and extragonadal sites (anterior mediastinum and pineal gland). "Luzp4 was originally discovered using the SEREX technique, whereby circulating antibodies from a seminoma patient were used for expression screening of testis cDNA libraries." (PMID 25662211, 2015).
vitiligo (1 paper, 2024). Generalized well circumscribed patches of leukoderma that are generally distributed over symmetric body locations and is due to autoimmune destruction of melanocytes. "Phospholipase C Eta 2 (PLCH2) expression was upregulated in stable vitiligo patients, and significant downregulation of leucine zipper protein 4 (LUZP4) in progressive vitiligo patients was seen." (PMID 38715599, 2024). "The mechanisms of how PLCH2 or LUZP4 could be involved in inflammation and vitiligo remains unclear." (PMID 38715599, 2024).
cancer (5 papers, 2015 to 2022). A tumor composed of atypical neoplastic, often pleomorphic cells that invade other tissues. "LUZP4 was originally characterized as a cancer/testis antigen, which represents a group of poorly characterized proteins whose expression is normally restricted to testis but are frequently up-regulated in cancer cells." (PMID 27679854, 2016). "The marked reduction in metastatic capacity and cancer cell proliferation following ALYREF, THOC1 and LUZP4 depletion further suggests that there may be therapeutic benefit in targeting TREX." (PMID 27679854, 2016).
tumour (3 papers, 2006 to 2020). "Some of the identified prognostic DE RBPs have been reported associated with tumor progression, such as RBM47, LUZP4, AFF3, PPARGC1A, PPARGC1B, PABPC3, and PNLDC1." (PMID 33224957, 2020). "Generally, the expression levels for Luzp4 mRNA were low compared with Alyref and Uif, although we observed at least one tumour biopsy that showed increased Luzp4 expression within most tissue types." (PMID 25662211, 2015). "Since Luzp4 was originally described as a CTA we examined Luzp4, Alyref and Uif expression in tumour biopsies from 402 different patients, representing multiple different clinical stages of tumours from a wide range of tissues." (PMID 25662211, 2015). "Therefore, given the potential functional redundancy between Alyref and Luzp4, it seems plausible that in certain tumours, Luzp4 may function to promote the export of mRNAs which would normally utilize Alyref." (PMID 25662211, 2015).
LUZP4 also shares sentences with these, for which no sentence is quoted: glioma (2 papers); lung carcinoma (2); ovarian carcinoma (2); astrocytomas (1); brain tumour (1); hematological malignancies (1); oligoastrocytoma (1); viral infection (1).